SKA1 (spindle and kinetochore associated complex subunit 1)
Diseases named in the same sentence as SKA1 in open-access papers (continued):
Sharing a sentence is not in itself a finding about the gene and the disease.
glioma (continued). "Moreover, analysis of TCGA dataset showed significant increase of SKA1 expression in grade IV glioma compared with those in grade III glioma and grade II glioma." (PMID 31827398, 2019). "Based on these findings, we further investigated the biological functions of SKA1 in glioma and figured out that it could significantly promote glioma cells proliferation, migration and invasion abilities." (PMID 31827398, 2019). "To further confirm these results, we examined the expression of SKA1 at protein level with tissue samples collected from Nanfang hospital, including glioma tissues (grade II, n = 5; grade III, n = 8; grade IV, n = 34) and non-tumor brain tissues (n = 5) with Western blot." (PMID 31827398, 2019). "Furthermore, the K-M curve analysis of SKA complex in patients with gliomas included in the GEPIA database demonstrated that the patients with gliomas who have higher expressions of SKA1 and SKA3 tend to have shorter OS than those with lower expression (p < 0.01)." (PMID 35095717, 2021). "GSEA results showed that SKA1 might be involved in cell cycle phase transition in glioma." (PMID 31827398, 2019). "A significant overexpression of the mRNA levels of SKA1 and SKA3 was found in WHO Grade 4 (G4) as compared to G3 and G2 gliomas." (PMID 35095717, 2021). "Based on the results, there are much more related genes identified with SKA1 and SKA3, but less genes for SKA2 in gliomas." (PMID 35095717, 2021). "More likely, SKA1 and SKA3 played a more crucial role compared to SKA2 in those identified pathways for gliomas." (PMID 35095717, 2021). "It has been observed that there is a statistically significant overexpression of the mRNA levels of SKA1, SKA2, and SKA3 in tumors as compared to normal tissues of patients with glioma included in the UALCAN database using Wilcoxon rank sum tests (p < 0.01)." (PMID 35095717, 2021). "We found a significant overexpression of the mRNA levels of SKA1, SKA2, and SKA3 in patients with glioma patients." (PMID 35095717, 2021). "Therefore, SKA1 could be a promising therapeutic target for the treatment of human gliomas." (PMID 31827398, 2019). "Moreover, overexpression of SKA1 may lead to poor prognosis in glioma." (PMID 31827398, 2019). "To provide further insights into the mechanisms of SKA1 regulation, we used GSEA to investigate the possible biological functional of SKA1 in glioma with public dataset, including TCGA database and GEO dataset." (PMID 31827398, 2019). "Interestingly, the expression of SKA1 and SKA3 was negatively correlated with OS in WHO G3 gliomas (p < 0.001 and P = 0.002, respectively)." (PMID 35095717, 2021). "The mRNA levels of SKA1, SKA2, and SKA3 were significantly upregulated in gliomas." (PMID 35095717, 2021). "This could be an indication that SKA1 and SKA3 are better prognostic biomarkers for gliomas." (PMID 35095717, 2021). "Furthermore, it is demonstrated that knockdown of SKA1 led to cell-cycle arrest and MET in glioma." (PMID 31827398, 2019). "Higher expression of SKA1 and SKA3, but not SKA2, was significantly correlated with shorter overall survival of patients with glioma." (PMID 35095717, 2021). "However, the clinical value of SKA complex (SKA1, SKA2, and SKA3) as a prognostic biomarker in gliomas has not been investigated fully." (PMID 35095717, 2021).
clear cell renal cell carcinoma (2 papers, 2021 to 2022). "In clear cell renal cell carcinoma, our data convincingly demonstrated a mechanism by which SKA1 promotes tumor metastasis through SAFB-mediated transcriptional repression of DUSP6." (PMID 36462498, 2022).
Fanconi anemia (2 papers, 2022 to 2025). Fanconi anemia (FA) is a hereditary DNA repair disorder characterized by progressive pancytopenia with bone marrow failure, variable congenital malformations and predisposition to develop hematological or solid tumors. "Our results suggest that in HCCs, SKA1–3 participate in the Fanconi anemia pathway, homologous recombination, spliceosome, DNA replication, and cell cycle signaling pathway." (PMID 36439516, 2022). "The analyses of Kyoto Encyclopedia of Genes and Genome (KEGG) and Gene ontology (GO) demonstrated that SKA1–3 are enriched mainly in the Fanconi anemia, homologous recombination, spliceosome, DNA replication, and cell cycle signaling pathways." (PMID 36439516, 2022). "The results from KEGG analysis indicated that the SKA1–3 co-expressed genes regulated the Fanconi anemia pathway, homologous recombination, cell cycle signaling pathway, spliceosome, and DNA replication." (PMID 36439516, 2022). "The analysis of KEGG demonstrated that the genes co-expressed with SKA1–3 were involved in regulating the Fanconi anemia pathway, homologous recombination, spliceosome, DNA replication, and cell cycle signaling pathway." (PMID 36439516, 2022). "In addition, SKA1–3 may affect HCC prognosis via the Fanconi anemia pathway, homologous recombination, spliceosome, DNA replication, and cell cycle signaling pathway." (PMID 36439516, 2022).
glioblastoma (2 papers, 2018 to 2019). The most malignant astrocytic tumor (WHO grade IV). "In vitro experiments revealed that SKA1 may be a potential therapeutic target of human glioblastoma, but the underlying mechanisms remains to be elucidated." (PMID 31827398, 2019). "The area under the receiver operating characteristic (ROC) curve of SKA1 for differential diagnosis was 0.774 (95% CI 0.716–0.832), indicating that SKA1 could serve as an effective diagnosis marker to distinguish glioblastoma patients from non-GBM patients (Grade II and III)." (PMID 31827398, 2019).
lung adenocarcinoma (2 papers, 2021 to 2023). A carcinoma that arises from the lung and is characterized by the presence of malignant glandular epithelial cells. "Significantly, abnormal SKA1 protein levels were linked to poorer patient prognosis; thus, this biomarker has great promise for assessing the prognosis of people with lung adenocarcinoma." (PMID 37814813, 2023). "Its significance as a pathogenic component and possible marker for lung adenocarcinoma was supported by the dramatic upregulation of the SKA1 protein within clinical cancer tissue samples and the complicated linkage between several signaling pathways and the SKA1 protein." (PMID 37814813, 2023). "As we expected, upregulation of SKA1 expression was found in 85% (17/20) of the lung adenocarcinomas." (PMID 37814813, 2023). "Twenty lung adenocarcinoma tissues with paraneoplastic tissues, including 11 males and 9 females with a mean age of 62 years, were adopted to perform IHC staining of SKA1." (PMID 37814813, 2023). "Consequently, our forthcoming research will focus on elucidating the specific mechanism of SKA1 in lung adenocarcinoma." (PMID 37814813, 2023). "Additionally, we employed immunohistochemistry, a well-established and dependable technique for confirming disparities in SKA1 expression between lung adenocarcinoma and neighboring tissues." (PMID 37814813, 2023). "In addition, the SKA1 gene showed high sensitivity and specificity for the diagnosis of lung adenocarcinoma, suggesting the potential to offer novel insights and approaches for the individualization of lung cancer diagnosis." (PMID 37814813, 2023).
lung carcinoma (2 papers, 2020 to 2023). "Therefore, the objective of our study is to elucidate the intricate and diverse involvement of SKA1 in lung cancer." (PMID 37814813, 2023). "Besides, SKA1 has been reported to contribute to chemotherapy resistance in lung carcinoma through prevention of cisplatin-induced apoptosis." (PMID 33224872, 2020).
oral cancers (2 papers, 2013 to 2018). "In accordance with these reports, we found that SKA1 appears to be involved in oral carcinoma by regulating spindle checkpoint silencing and maintaining chromosome cohesion in mitosis." (PMID 23962337, 2013). "In order to investigate the role of SKA1 in oral cancer, we employed lentivirus-mediated shRNA to silence SKA1 expression in the CAL-27 human oral adenosquamous carcinoma cell line." (PMID 23962337, 2013). "However, until now, the precise role of SKA1 in oral carcinoma has remained unclear." (PMID 23962337, 2013). "However, the precise role of SKA1 in oral carcinoma remains unknown." (PMID 23962337, 2013). "Thus, SKA1 silencing by RNAi might be a potential therapy for oral carcinoma." (PMID 23962337, 2013).
osteosarcoma (2 papers, 2022 to 2024). A usually aggressive malignant bone-forming mesenchymal neoplasm, predominantly affecting adolescents and young adults. "Additionally, SKA1 inhibits FPGS transcription by physically interacting with RPB3 to cause osteosarcoma cells to become resistant to MTX." (PMID 36462498, 2022). "Additionally, hypoxia was found to promote chemotherapy resistance by downregulating the expression of the SKA1 in human osteosarcoma." (PMID 39030638, 2024). "Moreover, SKA1 prevents RNA polymerase II subunit RPB3 from activating FPGS transcription by interacting with RPB3, consequently inducing MTX-resistance in osteosarcoma patients." (PMID 36462498, 2022).
pancreatic cancer (2 papers, 2020). "In this study, we determined the high expression and possible tumorigenic role of SKA1 in pancreatic cancer cells in vitro and in vivo, and the underlying mechanisms and signalling pathways were explored by iTRAQ assay." (PMID 32232899, 2020). "Mechanistically, we demonstrated that SKA1 enhanced pancreatic cancer aggressiveness by inhibiting G2/M arrest and regulating actin cytoskeleton organization via activating Cdc42." (PMID 32232899, 2020). "However, currently, the expression and molecular function of SKA1 in human pancreatic cancer remain undefined." (PMID 32232899, 2020). "It has been reported that SKA1 overexpression may lead to the development of pancreatic cancer in mouse models." (PMID 33224872, 2020). "Next, we explored whether DNA methylation status influenced gene expression in 185 pancreatic cancer samples by analyzing 11 and 15 CpG sites in the SKA1 and SKA3 DNA locus, respectively." (PMID 33224872, 2020). "SKA1 (identified as EMT‐related dysregulated protein in PDAC cells) is expressed in various types of tumours; however, whether SKA1 expression is involved in pancreatic cancer development remains unknown." (PMID 32232899, 2020). "We find that SKA1 and SKA3 expression correlates with prognosis and immune cell infiltration in PDAC, highlighting their potential as pancreatic cancer prognostic biomarkers." (PMID 33224872, 2020).
epilepsy (1 paper, 2018). A brain disorder characterized by episodes of abnormally increased neuronal discharge resulting in transient episodes of sensory or motor neurological dysfunction, or psychic dysfunction. "Spindle and kinetochore associated complex subunit 1 (SKA1), has been suggested as being involved in human brain development; however, its participation in epilepsy has not been studied." (PMID 29958461, 2018).
kidney cancer (1 paper, 2021). Primary or metastatic malignant neoplasm involving the kidney. "In addition, the mRNA levels of SKA1, SKA2, and SKA3 were significantly overexpressed in several other tumors, including breast, lung, colorectal, and kidney cancer." (PMID 35095717, 2021).
ovarian carcinoma (1 paper, 2022). A malignant neoplasm originating from the surface ovarian epithelium. "Eight genes (NUF2, GTSE1, DEPDC1, KIF18B, PBK, CEP55, HJURP, SKA1) were potential hub genes correlated to ovarian cancer progression." (PMID 35173547, 2022).
Pan (1 paper, 2021). "Meanwhile, the results in the Timer database also verified that the expressions of SKA1/2/3 were generally upregulated in Pan-cancer." (PMID 34845974, 2021).
renal carcinoma (1 paper, 2022). A carcinoma arising from the epithelium of the renal parenchyma or the renal pelvis. "Our findings may provide a new way of researching SKA1-regulated tumor metastasis, and indicate that SKA1 is a prospective therapeutic target for renal carcinoma." (PMID 36462498, 2022). "It turned out that in comparison to normal renal tubule epithelial cells HK-2, RCC cell lines 786-O, 769-P, ACHN, Caki-1, and OS-RC-2 displayed greater SKA1 mRNA and protein levels; nevertheless, endogenous SKA1 content did not significantly differ among these five renal cancer cell lines." (PMID 36462498, 2022).
cancer (22 papers, 2013 to 2026). A tumor composed of atypical neoplastic, often pleomorphic cells that invade other tissues. "Gene set enrichment analysis revealed that high levels of SKA1 are associated with cancer-promoting pathways." (PMID 37746945, 2023). "The obtained results revealed that the expression of SKA1/2/3 was positively associated with six cancer drugs but negatively correlated with the IC50 of 24 cancer drugs in GDSC." (PMID 37180139, 2023). "At the same time, our study also demonstrated a close association of SKA1/2/3 and drug sensitivity across cancers, suggesting a potential of SKA family genes and related pathways of biological functions as therapeutic targets." (PMID 37180139, 2023). "Previous studies have shown that overexpression of SKA1 is associated with a poor prognosis in various cancers." (PMID 37746945, 2023). "Our bioinformatics and immunohistochemical investigations of clinical cancer patient materials revealed that increased SKA1 expression was associated with a poor outcome for patients with ccRCC, which provided initial evidence for this role." (PMID 36462498, 2022). "SKA1 has garnered considerable interest in the field of malignancies, and it has been implicated in the development and spread of many cancer types." (PMID 36462498, 2022). "The SKA1 expression level is increased in non-small cell lung cancer and is associated with cancer progression by regulating cell proliferation, migration, and invasion." (PMID 36439516, 2022). "The overexpression of SKA1 has been found to be significantly associated with early recurrence and progression in several different cancer cells." (PMID 35095717, 2021). "Our data also associated high SKA1 expression with advanced cancer phenotypes such as stage II, G3 + G4, and patients survived with tumor." (PMID 33224872, 2020). "Previous TCGA data analysis has shown that SKA1 mutations or copy number variations occur at a very low frequency in various cancer types." (PMID 30537941, 2018). "We next assessed the copy number variants (CNVs) of SKA1/2/3 across cancers." (PMID 37180139, 2023). "In this study, we conducted a comprehensive analysis of SKA1/2/3 at the pan-cancer level, including gene alterations (mutation, copy number, methylation), expression, prognostic value, pathway enrichment, effects on the tumor microenvironment (TME) and immunotherapy." (PMID 37180139, 2023). "Notably, SKA1/2/3, as new cancer-related genes, has been implicated in the progression of numerous cancer types." (PMID 34845974, 2021). "The association between SKA1 and cancer has been widely investigated." (PMID 33224872, 2020). "Moreover, future studies are needed to determine the precise mechanism underlying SKA1 regulation of oral adenosquamous cancer cell proliferation." (PMID 23962337, 2013). "Patients with high SKA1 level tend to have a poor prognosis probably due to the fetal liver cell-like gene expression profiles in cancer cells, and such gene profiling was associated with cell cycle and apoptosis pathways that may promote cancer cell proliferation." (PMID 30537941, 2018). "In the TIMER2.0 database, we examined the expression of SKA1 in 38 cancer types and discovered that SKA1 was substantially differentially expressed in the tumor group in numerous malignant tumor forms, including HCC (P < .001)." (PMID 37746945, 2023). "The effects of SKA1 co-expressed genes on the control of the cell cycle and oocyte meiosis in cancer and development were revealed by GO and KEGG enrichment analyses." (PMID 37746945, 2023).